PDPN (podoplanin)
Diseases named in the same sentence as PDPN in open-access papers (continued):
Sharing a sentence is not in itself a finding about the gene and the disease.
colon carcinoma (13 papers, 2007 to 2025). "Overall, these results demonstrated that TGF-β1, secreted by alternatively activated M2 macrophages, induces modifications in the stroma that support colon cancer cell growth, highlighting PDPN as a key mediator of these tumor-promoting alterations." (PMID 40842027, 2025). "The expression pattern we have observed for podoplanin, i.e., in stromal fibroblasts in colon cancer tissue and endothelial cells of lymphatic vessels in benign colon tissue, is in agreement with previous studies." (PMID 33917056, 2021). "Moreover, the analysis of a colon cancer database including 1336 tumor samples from 16 independent cohorts, revealed that PDPN expression was significantly correlated with shorter relapse-free survival." (PMID 40842027, 2025). "The inhibition of interaction between PDPN and CLEC-2 using an 8F11 monoclonal antibody for PDPN inhibits platelet aggregation and lung metastasis in mouse colon carcinoma." (PMID 40741180, 2024). "The fibroblasts and myofibroblasts were visualized by anti-human RGS5, decorin, podoplanin/gp36, CD36, α-SMA, and HHIP antibodies in colon mucosa and colon cancer tissues." (PMID 36463319, 2022). "The expression of LYVE-1 in colon cancer tissues and LYVE-1 and podoplanin antibody in frozen tumor tissues was observed." (PMID 31289961, 2019). "In order to investigate whether ZP2, Ki67, podoplanin, and EXOSC5 share the same tissue distribution, immunohistological analysis of colon cancer specimens has been performed." (PMID 33917056, 2021). "Two prognostic colon cancer biomarkers, namely podoplanin and exosome component 5 (EXOSC5), have been chosen to further verify tumor and normal tissue specimens: podoplanin mRNA level was significantly increased by 10-fold in tumor samples, and EXOSC5 by even 20-fold." (PMID 33917056, 2021). "Podoplanin and EXOSC5 were shown to be more highly expressed in colon cancer as well, although to a minor extent compared to our study, which could be due to a lower number of tissue samples." (PMID 33917056, 2021).
gastric cancer (13 papers, 2010 to 2025). A primary or metastatic malignant neoplasm involving the stomach. "In gastric cancer tissues and cell lines, it was found that PDPN was upregulated and was associated with poor disease prognosis." (PMID 40741180, 2024). "A recent study suggests that periostin secreted by podoplanin positive-CAFs induces metastasis and stemness in gastric cancer cells through PI3K/AKT and FAK/YAP activation, respectively." (PMID 38562556, 2024). "As a result, there is a positive feedback loop between PDPN-positive CAFs and cancer stem cells in gastric cancer, leading to gastric cancer progression." (PMID 40741180, 2024). "For instance, high expression of PDPN not only predicts poor survival outcomes but also shows correlations with immune markers of TAMs and T cell exhaustion in gastric cancer." (PMID 33790966, 2021). "In this study, to investigate the roles of activated GCAFs in gastric cancer patients, we used HE staining combined with PDPN detection to trace GCAFs, and FAP was employed to indicate the activation state of GCAFs." (PMID 30038550, 2018). "Other studies concerning astrocytic and gastric carcinomas, lung squamous cancer and other malignancies, have demonstrated the involvement of podoplanin in cell migratory activity necessary for metastasis." (PMID 24797369, 2014). "Knockdown of PDPN resulted in the depression of ezrin in gastric cancer cell lines." (PMID 40741180, 2024). "Together, this study elucidates the mechanism by which PDPN(+) CAFs promote angiogenesis, providing a deeper understanding of the molecular processes underlying CAF‐mediated angiogenesis and suggesting potential therapeutic targets for gastric cancer treatment." (PMID 39764562, 2025). "Podoplanin, a transmembrane protein interacting with RhoA, is another mediator of CAF-induced gastric cancer invasion." (PMID 38562556, 2024). "For instance, it was demonstrated that PDPN-positive CAFs secreted periostin, which activates FAK/YAP signaling in gastric cancer cells, resulting in activation of the PI3K/AKT pathway, which positively regulates periostin." (PMID 40741180, 2024).
Oral leukoplakia (13 papers, 2010 to 2026). A thickened white patch on the oral mucosa that cannot be rubbed off. "These mechanistic insights align closely with our findings, in which both serum and salivary PDPN levels showed a clear stepwise increase from controls to leukoplakia to OC, and exhibited excellent diagnostic performance in ROC analyses." (PMID 41594182, 2026). "In conclusion, our evidence-based systematic review and meta-analysis demonstrates that podoplanin overexpression behaves as a biomarker of malignant transformation risk in the epithelium of oral potentially malignant disorders, singularly in oral leukoplakia." (PMID 41228241, 2025). "We can now also state on the basis of the evidence that oral leukoplakias that overexpress podoplanin have a risk of malignancy more than three times higher than those that do not overexpress this protein." (PMID 41228241, 2025). "The purpose of this study is to evaluate the expression of podoplanin in oral leukoplakia as a biomarker for cancer risk assessment and correlation of podoplanin with grades of OSCC." (PMID 26558136, 2015). "Oral leukoplakia was the most investigated lesion, and for which there is the most evidence for the predictive value of podoplanin overexpression, which was significantly associated with an increased malignant transformation risk (RR = 3.37, 95% CI = 2.13–5.32, p < 0.001; 7 studies/558 patients)." (PMID 41228241, 2025). "Interestingly, podoplanin, a small mucin-type transmembrane protein that modulates molecular pathways of cell migration and invasion, is over-expressed in dysplastic oral leukoplakia and associated with grade of dysplasia and risk of progression to cancer." (PMID 24403051, 2014). "If the present study results could be supported by further studies, analysis of the podoplanin expression in the biopsied tissues could be helpful to clinicians and patients in evaluating the cancer risk in oral leukoplakia and as a biomarker for advanced grades of OSCC." (PMID 26558136, 2015). "Salivary PDPN levels showed a similar pattern, being highest in OC (2.65 ± 0.75 ng/mL), followed by leukoplakia (1.40 ± 0.45 ng/mL), and controls (0.72 ± 0.30 ng/mL) (p < 0.001)." (PMID 41594182, 2026). "This aligns strongly with the present study, in which both serum and salivary PDPN levels increased progressively from control to leukoplakia to OC, and were identified as independent predictors of malignancy." (PMID 41594182, 2026). "Despite the importance of this topic, evidence from systematic reviews and meta-analyses on the implications of podoplanin in the malignant transformation of OPMDs remains limited and derives mainly from oral leukoplakias." (PMID 41228241, 2025). "Among these biomarkers, podoplanin emerges as a promising biomarker with potential predictive value of malignant transformation in oral leukoplakias." (PMID 41228241, 2025). "Podoplanin also proved to be a valuable biomarker in the malignant transformation of all investigated OPMDs (oral leukoplakia: p < 0.001; erythroplakia: p = 0.05; oral lichen planus: p = 0.02; discoid lupus erythematosus: p = 0.009)." (PMID 41228241, 2025). "Both investigations concluded that podoplanin is one of the most promising and predictive biomarkers of the malignant transformation of oral leukoplakias." (PMID 41228241, 2025).
Oral leukoplakia (continued). "In the present study, we analyzed the immunohistochemical expression of podoplanin in 20 cases each of oral leukoplakia, OSF, OSCC and normal mucosa, and correlated it with clinicopathological parameters." (PMID 29410757, 2017). "Podoplanin expression in the samples of oral submucous fibrosis was higher than that in oral leukoplakia." (PMID 29410757, 2017). "Positive expression of podoplanin was observed in 65% of leukoplakia cases whereas 90% of OSF cases were podoplanin positive." (PMID 29410757, 2017). "The expression of podoplanin in OSF was 90%; which was much higher than that in leukoplakia (65%), probably suggesting its increased risk of malignant transformation." (PMID 29410757, 2017). "The purpose of our study was to compare the imunohistochemical expression of podoplanin in oral leukoplakia, oral submucous fibrosis(OSF) and OSCC with that in normal mucosa." (PMID 29410757, 2017). "In the present retrospective study, podoplanin expression was investigated immunohistochemically in 40 patients each of oral leukoplakia and OSCC." (PMID 26558136, 2015). "The most significant findings of this study demonstrate that both serum and salivary PDPN levels increase progressively from healthy controls to leukoplakia and reach their highest values in patients with OC, indicating a strong association with disease severity." (PMID 41594182, 2026). "Thus, results show that there is increased podoplanin expression with increasing dysplasia in oral leukoplakia patients and also podoplanin expression score increases from well-differentiated OSCC to poorly differentiated OSCC." (PMID 26558136, 2015). "Furthermore, it has been proposed that podoplanin might serve as a potential clinical marker for the malignant progression of oral leukoplakia, and it is regarded as a novel myoepithelial marker in salivary gland tumors." (PMID 24797369, 2014). "Comparison of grades of podoplanin expression among oral leukoplakia, OSF and OSCC with that in normal mucosa using Kruskal-Wallis test showed that the variation in the grades of podoplanin expression among groups was significant at 0.000 level." (PMID 29410757, 2017). "In our study also, there was a statistically significant variation in the grades of podoplanin expression in OSCC (100%), OSF (90%) and oral leukoplakia (65%) when compared to that in normal mucosa (35%)." (PMID 29410757, 2017). "We demonstrated a progressive elevation of serum and salivary PDPN levels from controls to leukoplakia and overt OC, paralleling the shift from non-dysplastic to dysplastic and invasive phenotypes described in SRC- and RAS-driven oncogenic signaling." (PMID 41594182, 2026). "This study also showed that 58% of oral leukoplakia with positive PDPN progressed to OSCC, compared to only 23% of PDPN negative lesions (p = 0.010)." (PMID 35326482, 2022). "Among the 20 cases of oral leukoplakia, 13 cases (65%) showed a positive expression of podoplanin in the epithelium, whereas 7 cases (35%) were negative." (PMID 29410757, 2017).
seminoma (13 papers, 2011 to 2026). A radiosensitive malignant germ cell tumor found in the testis (especially undescended), and extragonadal sites (anterior mediastinum and pineal gland). "The intensity of POSTN and PDPN immunohistochemical reaction was stronger in Sertoli cell tumours and seminomas than in Leydig cell tumours." (PMID 41361308, 2025). "In addition, Ki67 antigen expression for both POSTN and PDPN correlated significantly with the number of positive cells and the intensity of the reaction in seminomas and Sertoli cell tumours." (PMID 41361308, 2025). "A previous study showed that PDPN is overexpressed in all seminoma cases." (PMID 35740662, 2022). "Our case exhibited positivity for Podoplanin (D2-40), a marker of lymphatic endothelium and mesothelial cells that can be expressed in Kaposi's sarcoma, in seminoma, in some cases of epithelioid hemangioendothelioma, and in the epithelioid variant of fibrous histiocytoma." (PMID 23691400, 2013). "Thus, PDPN can be a potential target molecule for NIR-PIT in the treatment of seminomas." (PMID 35740662, 2022). "In the present retrospective study, 186 canine testicular tumours namely 61 Leydig cell tumours, 64 Sertoli cell tumours and 61 seminomas and 10 normal canine testicles were immunohistochemically tested for expression of POSTN, PDPN and Ki67 antigens." (PMID 41361308, 2025). "Normal testes were negative for both POSTN and PDPN, whereas 27 (44.3%) Leydig cell tumours, 54 (84.4%) Sertoli cell tumours and 56 (91.8%) seminomas were cytoplasmically positive for POSTN and 23 (37.7%), 49 (77.6%) and 44 (72.1%) were cytoplasmically positive for PDPN respectively." (PMID 41361308, 2025). "The results showed the absence of expression of POSTN and PDPN in normal canine testes and their expression in neoplastic ones, suggesting a role for these proteins in the carcinogenesis of the testis and encouraging further studies, in particular, on seminomas and Sertoli cell tumours." (PMID 41361308, 2025).
esophageal squamous cell carcinoma (11 papers, 2013 to 2025). Esophageal squamous cell carcinoma (ESCC) is a type of esophageal carcinoma (EC) that can affect any part of the esophagus, but is usually located in the upper or middle third. "The expression of PDPN in tumor cell, especially in invasive edge cells, is bound up with poor prognosis in esophageal squamous cell carcinoma patients." (PMID 35659308, 2022). "Lack of PDPN significantly reduces cell motility and EMT-related aggressiveness in esophageal squamous cell carcinoma cells, demonstrating that PDPN is crucial for platelets-induced EMT." (PMID 35659308, 2022). "To gain insights into the malignant nature of PDPN in esophageal squamous cell carcinoma, in this study, we investigated the role of PDPN in EMT progression and invasion ability, especially focusing on the interaction with platelets, in human esophageal squamous cell carcinoma TE11 cells." (PMID 32581653, 2020). "However, the roles of podoplanin in esophageal squamous cell carcinoma (ESCC) are poorly understood." (PMID 26095281, 2015).
metastatic tumors (11 papers, 2014 to 2025). "Compared to primary tumors, both circITGB6 and PDPN showed increased expression in metastatic tumors, accompanied with increased TGFβ abundance." (PMID 37898647, 2023). "In both microscopic- and major-ENE, podoplanin expression and mean score were significantly higher in perinodal stroma than in intranodal metastatic tumor area (0.30 ± 0.675 vs. 2.00 ± 1.247; p = 0.001, 0.56 ± 1.042 vs. 1.83 ± 0.786, p < 0.001)." (PMID 35256682, 2022). "Podoplanin up-regulated in metastatic tumors has been proposed to promote CLEC-2 platelet activation and aggregation." (PMID 25368330, 2014). "Both podoplanin and vimentin regulate processes of cell motility and invasion, and their expression often correlates with metastatic disease, and poor prognosis." (PMID 24598827, 2014). "Although podoplanin expression often correlates with metastatic disease and poor prognosis, phosphorylation of serines in cytoplasmic domain of podoplanin has recently been shown to interfere with cellular motility and migration signaling." (PMID 24690739, 2014). "Podoplanin drives actomyosin contractility through the activation of RhoA/C GTPases in lymphoid fibroblasts and its high expression correlates with poor prognosis and higher incidence of metastatic disease." (PMID 36278174, 2022). "The levels of soluble podoplanin in plasma were found to increase in patients with different kind of cancers compared to normal individuals, as well as in patients with metastasis with respect to patients with non-metastatic tumors." (PMID 36278174, 2022). "In addition, myoepithelial markers (e.g. p63, cytokeratin 14, and calponin) and endothelial markers (e.g., podoplanin and CD31) may be useful for the differential diagnosis of in situ-like architecture in the metastatic tumors." (PMID 33593410, 2021). "In CAFs from metastatic tumors, a decrease in CCL2, MMP-2, TNC, OPN, and TGFβ levels and an increase in only TIMP1, PDPN, and SPP1 mRNA levels (without an effect on protein levels) was observed after calcitriol treatment." (PMID 38360633, 2024).
rheumatoid arthritis (11 papers, 2011 to 2025). A chronic, systemic autoimmune disorder characterized by inflammation in the synovial membranes and articular surfaces. "Co-culture strongly increased the expression of activation markers such as FAP, PDPN, HLA type 2, and IL-6—markers of a myofibroblast phenotype associated with chronic inflammation, as seen in conditions such as rheumatoid arthritis, and indicative of immune crosstalk." (PMID 41321638, 2025). "Similarly, PDPN expressed on the surface of pathogenic stromal fibroblasts found in arthritic joints has been proposed to be a therapeutic target for rheumatoid arthritis." (PMID 36304708, 2020). "Podoplanin is implicated in chronic inflammatory diseases, such as psoriasis, multiple sclerosis, and rheumatoid arthritis, promotes inflammation-driven and cancer-associated thrombosis, and stimulates cancer cell invasion and metastasis through a variety of strategies." (PMID 30736372, 2019). "Increased cell surface podoplanin (PDPN) expression has been described on the surface cancer-associated fibroblast cells and implicated in tumor cell invasiveness and on stromal fibroblasts collected from inflammatory joints of rheumatoid arthritis patients." (PMID 36304708, 2020). "In addition, increased podoplanin expression was observed in fibroblast-like synoviocytes and macrophages of rheumatoid arthritis patients with respect to patients with osteoarthritis and normal synovial tissue." (PMID 30736372, 2019). "In both clinical and experimental rheumatoid arthritis, ectopic lymphoid-like structures often develop at sites of chronic inflammation that correlate with the presence of Th17 cells, including a subpopulation of podoplanin-positive Th17 cells." (PMID 30736372, 2019). "Local infusion of CLEC-2 or podoplanin antibody in autoimmune diseases such as Multiple Sclerosis, rheumatoid arthritis may prove useful in suppressing inflammation." (PMID 26416420, 2015). "Thus, PDPN+FAPα+THY1+ cells play the role of an immune effector in the development of rheumatoid arthritis, capable of maintaining inflammation through the secretion of a different repertoire of chemokines and cytokines, as PDPN+FAPα+THY1− cells are capable of regulating osteoclast behavior." (PMID 38136590, 2023). "SF in the lining layer in rheumatoid arthritis (RA) expressed high levels of PDPN compared to the normal synovium, whereas CD248 expression was restricted to sub-lining layer cells." (PMID 27863512, 2016). "Applied to rheumatoid arthritis (RA), the aim is to study the interactions between synoviocytes and peripheral blood mononuclear cells (PBMC) with a focus on the Th17 pathway and to identify a mechanism which leads to high IL-17 secretion with an interest on podoplanin." (PMID 27338729, 2016).